IFT56 (intraflagellar transport 56)
Description:
Component of the intraflagellar transport (IFT) complex B required for transport of proteins in the motile cilium. Required for transport of specific ciliary cargo proteins related to motility, while it is neither required for IFT complex B assembly or motion nor for cilium assembly. Required for efficient coupling between the accumulation of GLI2 and GLI3 at the ciliary tips and their dissociation from the negative regulator SUFU. Plays a key role in maintaining the integrity of the IFT complex B and the proper ciliary localization of the IFT complex B components. Not required for IFT complex A ciliary localization or function. Essential for maintaining proper microtubule organization within the ciliary axoneme.
Synonyms: TTC26; FLJ12571; dyf-13; DYF13; BRENS
Tractability: PROTAC: ubiquitination databases record sites on it.
Gene: Protein-coding gene on chromosome 7 (139,133,744 to 139,191,986, forward strand). Ensembl gene ENSG00000105948.
Subcellular location: Cell projection, cilium
Subcellular location (Human Protein Atlas): Nucleoplasm; Cytosol; Mitochondria; Primary cilium
Pathways (Reactome):
Organelle biogenesis and maintenance: Intraflagellar transport
Gene Ontology:
Molecular function: intraciliary transport particle B binding
Biological process: cilium assembly; axoneme assembly; intraciliary anterograde transport; intraciliary transport; intraciliary transport involved in cilium assembly; protein localization to cilium; smoothened signaling pathway
Cellular component: cilium; intraciliary transport particle A; intraciliary transport particle B; ciliary basal body; ciliary base; ciliary tip; centrosome
Genetic constraint (gnomAD): Loss-of-function variants: 35 observed, 58.47 expected, observed/expected ratio (o/e) 0.6, 90% interval 0.46 to 0.79. The upper end of that interval is the gene's LOEUF score, 0.79, which puts it in group 3 of 6, group 1 being the genes least tolerant of losing a copy. Missense variants: 441 observed, 554.88 expected, observed/expected ratio (o/e) 0.79, 90% interval 0.73 to 0.86. Synonymous variants: 162 observed, 190.7 expected, observed/expected ratio (o/e) 0.85, 90% interval 0.75 to 0.97.
Homologues: Orthologues: chimpanzee IFT56 (99% identical), macaque IFT56 (99% identical), dog IFT56 (97% identical), mouse Ift56 (96% identical), rat Ift56 (96% identical), pig IFT56 (96% identical), guinea pig IFT56 (96% identical), rabbit IFT56 (94% identical), tropical clawed frog ift56 (86% identical), zebrafish ift56 (80% identical), Drosophila melanogaster Ttc26 (53% identical), Caenorhabditis elegans dyf-13 (38% identical).
Diseases named in the same sentence as IFT56 in open-access papers:
IFT56 is named in the same sentence as 14 diseases in open-access papers, as found by Europe PMC text mining. Sharing a sentence is not in itself a finding about the gene and the disease.
IFT56 shares sentences with these, for which no sentence is quoted: ciliopathies (6 papers); cholestasis (2); cancer (1); cystic kidney disease (1); developmental delay (1); fibrosis (1); genetic disease (1); Hydrocephalus (1); Jeune syndrome (1); kidney diseases (1); nephronophthisis (1); orofaciodigital syndrome (1); Senior-Loken syndrome (1); tumor (1).